KRT33A (keratin 33A)
Synonyms: K33A; HHA3-I; KRTHA3A; Ha-3I; Krt1-3; HA3I
Tractability: No criterion of Open Targets' tractability assessment is met for any kind of drug.
Gene: Protein-coding gene on chromosome 17 (41,346,092 to 41,350,828, reverse strand). Ensembl gene ENSG00000006059.
Subcellular location (Human Protein Atlas): Cytosol; End piece; Principal piece; Equatorial segment; Mid piece
Pathways (Reactome):
Developmental Biology: Formation of the cornified envelope; Keratinization
Gene Ontology:
Molecular function: structural constituent of skin epidermis; structural molecule activity
Biological process: epithelial cell differentiation; intermediate filament organization; morphogenesis of an epithelium
Cellular component: extracellular region; cytoskeleton; cytosol; keratin filament
Genetic constraint (gnomAD): Loss-of-function variants: 45 observed, 41.89 expected, observed/expected ratio (o/e) 1.07, 90% interval 0.85 to 1.38. The upper end of that interval is the gene's LOEUF score, 1.38, which puts it in group 5 of 6, group 1 being the genes least tolerant of losing a copy. Missense variants: 536 observed, 535.67 expected, observed/expected ratio (o/e) 1, 90% interval 0.93 to 1.08. Synonymous variants: 229 observed, 233.41 expected, observed/expected ratio (o/e) 0.98, 90% interval 0.88 to 1.1.
Homologues: Orthologues: macaque KRT33A (97% identical), rat Krt33a (91% identical), rabbit KRT33A (90% identical), rat Krt31 (90% identical), rat Krt33b (90% identical), dog KRT33B (89% identical), mouse Krt33a (89% identical), mouse Krt31 (88% identical), dog KRT31 (88% identical), mouse Krt33b (87% identical), pig KRT31 (86% identical), chimpanzee KRT33A (84% identical), and 1 more. Paralogues in human: KRT33B (94% identical), KRT31 (94% identical), KRT34 (88% identical), KRT35 (70% identical), KRT36 (70% identical), KRT32 (68% identical), KRT38 (61% identical), KRT40 (60% identical), KRT37 (59% identical), KRT39 (59% identical), KRT14 (50% identical), KRT16 (50% identical), and 56 more.
Diseases named in the same sentence as KRT33A in open-access papers:
KRT33A is named in the same sentence as 2 diseases in open-access papers, as found by Europe PMC text mining. Sharing a sentence is not in itself a finding about the gene and the disease. The quoted sentences say what the papers report.
tumor (2 papers, 2025). "The observed upregulation of DPEP3 and THRSP in high-grade tumors aligns with their established roles in tumor progression and metabolic reprogramming, while the downregulation of differentiation markers like KRT33A suggests a loss of epithelial characteristics in aggressive disease." (PMID 41155123, 2025). "The four most significantly downregulated genes in COM, compared to healthy tissue controls, were all keratin genes (KRT33A, KRT86, KRT34, and KRT38), which is consistent with a potential loss of epithelial differentiation, a hallmark of aggressive tumor behavior." (PMID 40647405, 2025).
KRT33A also shares sentences with these, for which no sentence is quoted: staphylococcus aureus infection (1 paper).